RNU6-724P (RNA, U6 small nuclear 724, pseudogene)
Gene: Small nuclear RNA gene on chromosome 5 (69,530,613 to 69,530,717, reverse strand). Ensembl gene ENSG00000212260.
Homologues: Orthologues: chimpanzee U6 (99% identical), macaque U6 (87% identical), guinea pig U6 (74% identical). Paralogues in human: RNU6-47P (84% identical), RNU6-411P (83% identical), RNU6-1011P (82% identical), RNU6-15P (82% identical), RNU6-33P (82% identical), RNU6-949P (82% identical), RNU6-1 (81% identical), RNU6-1060P (81% identical), RNU6-10P (81% identical), RNU6-116P (81% identical), RNU6-12P (81% identical), RNU6-13P (81% identical), and 1284 more.